EPO (erythropoietin)
Diseases named in the same sentence as EPO in open-access papers (continued):
Sharing a sentence is not in itself a finding about the gene and the disease.
malnutrition (continued). "It has been suggested that RDW increase is associated with impaired erythropoiesis due to underlying metabolic abnormalities such as oxidative stress, inflammation, malnutrition, dyslipidemia, erythrocyte fragmentation and impaired erythropoietin function." (PMID 33376644, 2020). "The participants were classified according to a diagnostic of PEW using the “Malnutrition Inflammation Score” (MIS) and bioimpedance analysis (BIA) measurement of body composition at the start of erythropoietin therapy and after 3 months of follow up." (PMID 31412807, 2019). "PEW is an incremental predictor of poor responsiveness to EPO in HD patients, thus, it is important to consider correcting malnutrition or wasting for a favorable response to treatment with EPO." (PMID 31412807, 2019). "It has been clearly shown that one of the most important factors for erythropoietin resistance is the presence of malnutrition and inflammation in HD patients." (PMID 24282790, 2013). "It was clearly shown that one of the most important factors for erythropoietin resistance is the presence of malnutrition and inflammation in HD patients." (PMID 24282790, 2013). "Resistance to erythropoietin (EPO) has been identified as a predictor of mortality risk, and associated with inflammation and malnutrition." (PMID 22768256, 2012). "One study divided HD patients into the PEW group and the non-PEW groups according to the malnutrition inflammation score (MIS); patients in the PEW group responded poorly to treatment with erythropoietin and tended to be more anaemic in combination with malnutrition." (PMID 38918730, 2024). "Elevated RDW-SD reflected a severe dysregulation of erythroid homeostasis, including abnormal erythropoiesis, which was attributed to multiple metabolic abnormalities such as oxidative stress, inflammation, malnutrition, erythrocyte fragmentation, and altered erythropoietin function." (PMID 35782962, 2022). "Well-nourished patients on MHD are less likely to develop folic acid deficiency as hemodialysis per se is not an indication for folic acid supplementation unless the patient is suffering from hyperhomocysteinemia, hyporesponsiveness to erythropoietin therapy, or malnutrition." (PMID 34886434, 2021). "Consistent with lower BMI suggesting malnutrition, altered iron metabolism, reduced production of erythropoietin and suppressed bone marrow activity could be the probable explanations for this phenomenon." (PMID 33911826, 2020). "Also, EPO resistance is related to inflammation and malnutrition." (PMID 26788441, 2016). "Generally, immunosuppression (from chronic dialysis), malnutrition, and the lack of erythropoietin increase the incidence of infection around the surgical and prosthesis sites." (PMID 36849583, 2023). "Although parenteral nutrition and erythropoietin were started on October 20, 2000 because of severe malnutrition and intestinal sub-occlusion, neither albumin and β-carotene serum levels nor hematologic parameters improved, and ascites increased." (PMID 37744114, 2021). "Compared to those without, patients with HF had a higher median malnutrition inflammation score, and mean erythropoietin resistance index." (PMID 34718902, 2021). "Although our study did not elucidate the role of IL-18 in the development of malnutrition and erythropoietin resistance in ESRD, we are sure it might be an interesting area for our future, larger studies." (PMID 36558477, 2022). "However, these conditions may be different with environment with high and adequate hemoglobin levels just by blood transfusion or high erythropoietin supplementations without correction of inflammation, oxidative stress and malnutrition." (PMID 23360132, 2013).
Sepsis (69 papers, 2005 to 2026). Sepsis is defined as life-threatening organ dysfunction caused by a dysregulated host response to infection. "Despite these findings, the mechanisms underlying the association between EPO and sepsis prognosis remain poorly understood." (PMID 40114237, 2025). "Our results are consistent with previous studies suggesting that elevated EPO levels are linked to poor outcomes in sepsis patients." (PMID 40114237, 2025). "Multivariate Cox proportional regression analysis and restricted cubic spline regression were employed to evaluate the association between EPO levels and 28-day mortality in sepsis patients." (PMID 40114237, 2025). "In rodent models of inflammation including sepsis and seizure, EPO protective activity was associated with increased eNOS, suppression of proinflammatory cytokines, and decreased iNOS expression." (PMID 36895793, 2023). "Furthermore, EPO treatment has been shown to improve survival in septic mice and mitigate lung injury and lethality in rat models of sepsis-associated ARDS." (PMID 40114237, 2025). "The incorporation of EPO measurements into clinical practice could improve the risk stratification and management of sepsis patients." (PMID 40114237, 2025). "Elevated EPO levels in patients with sepsis are associated with short-term prognosis and may serve as an early indicator of poor outcomes." (PMID 40114237, 2025). "Therefore, the efficacy in reducing the incidence of NEC-associated sepsis was ranked from best to worst as follows: lactoferrin, prebiotics, EPO, probiotics, arginine, glutamine, and placebo." (PMID 39315009, 2024). "Acute sepsis causes AI that is refractory to erythropoiesis-stimulating agents, thus administration of bacterial LPS abolishes iron use and erythropoiesis, even when LPS is administered with EPO analogs." (PMID 26068006, 2015). "Further research is necessary to clarify the underlying mechanisms and explore the potential therapeutic implications of EPO in the context of sepsis." (PMID 40114237, 2025). "In severe hypoxia, erythropoietin production can increase 1000-fold, but in critical illness, the erythropoietin response to low hemoglobin levels is impaired, especially in patients with sepsis and multiple trauma." (PMID 39941007, 2025). "Elevated EPO levels have also been observed in sepsis, where its anti-inflammatory and cytoprotective roles help attenuate immune dysregulation, oxidative stress, and tissue injury." (PMID 41012526, 2025). "Sepsis induces a state of systemic inflammation and widespread tissue hypoxia due to impaired perfusion, resulting in increased EPO production as the body attempts to rectify these deficits." (PMID 40114237, 2025). "The administration of a monoclonal anti-HMGB1 antibody after sepsis onset in mice partially restored EPO signaling in vivo." (PMID 39591250, 2024). "The same trend was observed for EPO mRNA expression (EPO–day of sepsis, p = 0.10, rs = 0.34; EPO–day of shock, p = 0.08, rs = 0.36)." (PMID 37367740, 2023). "Our results depict a tendency for correlation of EPO mRNA expression with the day of sepsis and septic shock development." (PMID 37367740, 2023). "This is likely to reflect the changes in erythropoietin responsiveness that accompany critical illness and sepsis in ESKD patients." (PMID 36522333, 2022). "Performing a multivariate analysis, ROP was found to be associated only to intraventricular hemorrhage and erythropoietin therapy, while AP-ROP was found to be associated to gestational age and sepsis." (PMID 35884908, 2022). "Collectively, our results reveal a novel role for EPO in mediating functional re-programming of endotoxin-tolerant macrophages; thus, targeting EPO appears to be a new therapeutic option in sepsis and other inflammatory disorders." (PMID 36016936, 2022).
Sepsis (continued). "The contrasting EPOR longitudinal profiles between severe and mild patients in our cohort are likely to reflect the changes in erythropoietin responsiveness that accompany critical illness and sepsis in ESKD patients." (PMID 36522333, 2022). "We established a mouse sepsis model by i.p. injection of E. coli to LPS-tolerized mice, and our results indicate that pretreatment of EPO mediated endotoxin-tolerant re-programming and protected mice from secondary infection of E. coli." (PMID 36016936, 2022). "Of these, erythropoietin is the farthest along in the developmental pipeline, as it has been used as a successful treatment in preclinical sepsis models." (PMID 35163625, 2022). "Whereas, haemoglobin and platelet are decreased in sepsis patients due to decreased erythropoietin levels and the megakaryocytopoiesis process." (PMID 35770922, 2022). "In parallel, patients with sepsis-AKI who were treated with the high-dose EPO showed favorable outcomes, particularly the 29-day mortality rate." (PMID 34831360, 2021). "An increased dose of EPO is necessary to maintain hematocrit (Hct) during septicemia, perhaps due to sepsis-reduced EPOR." (PMID 34831360, 2021). "Sepsis is a potent inducer of EPO from kidneys, as demonstrated by increased serum EPO in both the cecal ligation and puncture (CLP) and LPS models." (PMID 34831360, 2021). "During CLP sepsis, serum EPO level increased up to 20–40-fold and 5–8-fold in mice with normal kidney and low renal mass (5/6Nx), respectively, which still was not enough to maintain Hct in CLP mice." (PMID 34831360, 2021). "As such, increased endogenous EPO was demonstrated in all sepsis models, including BiNx-CLP despite the reduced liver erythropoietin receptor (EPOR), using Western blot analysis and gene expression, in liver (partly through hepatocyte apoptosis)." (PMID 34831360, 2021). "Despite the EPO resistance from uremia, EPO effectively maintained Hb concentration and attenuated sepsis with the comparable red-cell transfusions even with the inferior renal function compared with the non-EPO group." (PMID 34831360, 2021). "In hepatocytes, both LPS and inflammatory cytokines increased EPOR, perhaps trying to increase hepatic EPO production during sepsis for counteracting against hypotension and/or hepatocyte apoptosis." (PMID 34831360, 2021). "Because of the availability of EPO in current clinical practice, we proposed a short-course and high-dose EPO as an adjuvant therapy for sepsis." (PMID 34831360, 2021). "Because of the possible anti-inflammatory effect of EPO from the mouse models, a retrospective study in patients was performed to explore the possible correlation between EPO administration and sepsis outcomes." (PMID 34831360, 2021). "Second, there was a lack of a relationship between EPO levels in accordance with EPO dose and sepsis status." (PMID 34831360, 2021). "EPO was shown to prevent sepsis-related AKI in a rat model by inhibiting NF-κB and upregulating endothelial nitric oxide synthase (eNOS)." (PMID 32414157, 2020). "Patients with sepsis showed significant decreases in hemoglobin, plasma iron and sTfR/log ferritin and significant increases in plasma EPO, sTfR, hepcidin, ferritin and IL-6 on days 1, 3 and 7 of ICU admission compared with healthy volunteers." (PMID 31183575, 2019). "Binary logistic regression analysis showed that plasma EPO, hepcidin, ferritin, IL-6, sTfR/log ferritin, RDW and SOFA score were associated significantly with 28-day mortality in patients with sepsis." (PMID 31183575, 2019). "One clinical trial is ongoing to test the effect of EPO on microcirculatory alterations (NCT1087450) during sepsis." (PMID 29977234, 2018). "Hemorrhagic shock and sepsis-induced AKI in rats result in EPO-EPO receptor-dependent upregulation of Fgf23 mRNA levels in the bone marrow." (PMID 30405444, 2018). "Recent studies demonstrated the beneficial effect of EPO or EPO analogs after acute lung injury or during sepsis." (PMID 25352847, 2014).
Sepsis (continued). "Another study confirmed that the synthesis of nitric oxide as a result of EPO treatment is able to protect rats with sepsis by inhibiting the nuclear factor-κB pathway." (PMID 24926362, 2014). "What is more, rats used in their experiments were sepsis-induced by LPS prior to EPO administration." (PMID 24920275, 2014). "At the univariate analysis GA (p = 0.008), BW (p = 0.007), PDA (p =0.002), IVH (p = 0.001), early and late onset sepsis (p = 0.001), BPD (p = 0.002) and EPO therapy (p < 0.001), showed a significant association with the occurrence of ROP." (PMID 23837411, 2013). "Of note, by inhibiting pro-inflammatory immune effector pathways, EPO significantly reduces the survival of mice in a Salmonella (S.)Typhimurium sepsis model." (PMID 22094132, 2012). "The placebo group was significantly younger than those treated with EPO, and a significant proportion of the EPO-treated group (23.8%) had sepsis." (PMID 21943500, 2011). "First, hepcidin can abrograte erythroid colony formation in situations where erythropoietin concentrations are reduced, as is the case during sepsis." (PMID 21219610, 2011). "• Erythropoietin has a potential clinical application in the improvement of tissue bioenergetics during sepsis." (PMID 17509156, 2007). "Future research should aim to elucidate the mechanistic pathways linking EPO to sepsis outcomes." (PMID 40114237, 2025). "In this study, we investigated the prognostic value of EPO in sepsis patients admitted to the ICU." (PMID 40114237, 2025). "Restricted cubic spline analysis further validated the nonlinear relationship between EPO levels and mortality risk, underscoring its potential as a prognostic marker in sepsis." (PMID 40114237, 2025). "However, a study has reached the opposite conclusion, and the correlation between EPO and the prognosis of patients with sepsis is controversial." (PMID 40114237, 2025). "Investigating the role of EPO in the inflammatory and immune responses during sepsis could provide deeper insights into its impact on patient prognosis." (PMID 40114237, 2025). "Elevated EPO levels in patients with sepsis are correlated with unfavorable prognoses and may function as a prognostic biomarker for adverse outcomes." (PMID 40114237, 2025). "However, the clinical relevance of circulating EPO in sepsis progression and outcomes remains contentious and requires further elucidation." (PMID 40114237, 2025). "This study integrates data from 89 RCTs on six interventions (including probiotics, prebiotics, arginine, lactoferrin, EPO, and glutamine), utilizing NMA to evaluate their impact on NEC incidence, NEC-associated sepsis and mortality, and to rank their probabilities of efficacy." (PMID 39315009, 2024). "Additionally, in patients who developed sepsis, EPO and ISG15 mRNA expression levels at the time of ICU admission were positively correlated." (PMID 37367740, 2023). "Identifying EPO-related pathways involved in re-programming may lead to potential targets for sepsis treatment." (PMID 36016936, 2022). "High-dose erythropoietin may be beneficial for some patients with sepsis-AKI possibly through anti-inflammatory effects in macrophage." (PMID 36262286, 2022). "This increase appears to be a beneficial response, as treatment with exogenous erythropoietin or its analogues has been shown to be beneficial in multiple preclinical models of sepsis through its pleiotropic protective effects, including its ability to modulate the immune response." (PMID 35163625, 2022). "Given the success of erythropoietin treatment in preclinical models of sepsis, it is possible that such treatment could be beneficial in some sepsis patients, though there are not any published data yet to support this." (PMID 35163625, 2022). "The kidney can also produce molecules that could potentially improve sepsis outcomes, such as erythropoietin, vitamin D and uromodulin." (PMID 35163625, 2022).
Sepsis (continued). "In conclusion, high-dose EPO attenuated sepsis with preconditioning renal injury in mice possibly through the macrophage anti-inflammatory effect, which might be beneficial in some patients." (PMID 34831360, 2021). "Moreover, sepsis induced EPO production in mice with a limited renal mass (5/6Nx), despite being at a lower level than sepsis in normal kidneys and possibly induced hepatic EPO as increased EPO in mice with removed kidneys (BiNx)." (PMID 34831360, 2021). "Sepsis, in all tested mouse models, enhanced the endogenous serum EPO." (PMID 34831360, 2021). "The necessity of a high dose of EPO for its anti-inflammatory effect in sepsis might be due to the reduced EPOR in macrophages." (PMID 34831360, 2021). "Interestingly, EPO attenuated sepsis in CLP mice with kidney removal, supporting the extrarenal beneficial effect of EPO during sepsis." (PMID 34831360, 2021). "This also supports the requirement of the high-dose EPO for sepsis immunomodulation." (PMID 34831360, 2021). "The necessity of high-dose EPO is partly due to the LPS-induced EPOR downregulation in sepsis." (PMID 34831360, 2021). "Hence, high-dose and short-course EPO administration in sepsis is an interesting sepsis adjuvant therapy." (PMID 34831360, 2021). "Also, erythropoietin, a glycoprotein hormone member of cytokine I family, was tested in preclinical approaches of sepsis and malaria." (PMID 35250433, 2021). "Interestingly, while high-dose EPO attenuated serum cytokines in all sepsis models, low-dose EPO reduced only serum TNF-α and IL-10 in BiNx-CLP mice." (PMID 34831360, 2021). "Moreover, the data on EPO effects in sepsis superimposed with pre-existing renal dysfunction are lacking despite the increasing incidence of sepsis in patients with CKD who currently use EPO." (PMID 34831360, 2021). "In contrast to the previous studies, EPO administration before sepsis might be beneficial in the early phase of sepsis or septic shock, as demonstrated by the lower VDI, at least during the first 72 h of sepsis." (PMID 34831360, 2021). "Because of several non-erythropoiesis properties of EPO, increased endogenous EPO production in sepsis might not only be a response to renal hypoxia but also for the other protective purposes." (PMID 34831360, 2021). "EPO levels are usually low in critically ill patients but were shown to elevate in sepsis patients." (PMID 29977234, 2018). "EPO and G-CSF treatments seem to be deleterious during sepsis." (PMID 29977234, 2018). "Plasma EPO was increased only in AKI cases that were complicated with sepsis." (PMID 25524453, 2014). "Erythropoietin levels may be higher in patients with sepsis; erythropoietin levels decrease after PMX hemoperfusion and could be a prognostic indicator in patients with septic shock." (PMID 24249974, 2013). "In CLP-induced sepsis, erythropoietin can increase capillary perfusion in skeletal muscle." (PMID 22235348, 2012). "Previous experimental studies have also shown that erythropoietin is renoprotective in sepsis." (PMID 22235348, 2012). "Erythropoietin can protect organs against ischemia and sepsis." (PMID 22235348, 2012). "For example, the EPO group were older and more likely to have sepsis (p < 0.05)." (PMID 21906325, 2011). "Sepsis could impair production of erythropoietin by several mechanisms, including release of proinflammatory mediators that negatively impact erythropoiesis." (PMID 16965637, 2006). "This suggests that EPO could be a valuable addition to existing prognostic tools for sepsis." (PMID 40114237, 2025). "In addition, exploring therapeutic interventions targeting EPO pathways may offer new strategies for improving sepsis management and patient outcomes." (PMID 40114237, 2025).